CD44 (CD44 molecule (IN blood group))
Diseases named in the same sentence as CD44 in open-access papers (continued):
Sharing a sentence is not in itself a finding about the gene and the disease.
tumor (continued). "Taken together, these findings suggested that tumor cell surface receptor CD44 plays an important role in responding to tumor microenvironment-associated ligands, including SRGN, to potentiate cancer cell aggressiveness via triggering cytoskeleton remodeling and pro-survival pathway." (PMID 31898491, 2020). "Similarly, a subpopulation of tumor cells isolated from prostatectomy specimens express higher levels of tumor-associated calcium signal transducer 2 (Trop2), CD44, and CD49f, and show increased sphere-forming ability and regeneration capability in mice." (PMID 32754615, 2020). "Besides this, many studies have shown that CD44 can serve as a marker for cancer stem cells, which are closely associated with tumor recurrence, migration, and drug resistance due to their outstanding self-regulation." (PMID 34123080, 2020). "Importantly, the level of CPAP mRNA was positively associated with the expression of CD44 and IL-8 mRNAs in tumor tissue with vascular invasion." (PMID 31511651, 2020). "Recent findings link the expression of different CD44 isoform variants with cancer progression and specific tumor cell features, including pro-survival signaling, cellular reprogramming, acquisition of migratory capacity, and tumor initiation." (PMID 31623163, 2019). "In addition, CD44+ tumor was associated with increased recruitment of MDSCs, but attenuated recruitment of TILs." (PMID 31315262, 2019). "In addition, HCC CTCs were counterstained using cancer stem cell (CSC) marker, CD44, which have been found to be tightly linked with tumor initiation, recurrence, and metastasis through their self-renewal and survival advantages." (PMID 31819089, 2019). "NEPC tumor cells commonly express CD44, a putative cancer stem cell-associated marker." (PMID 30669516, 2019). "Importantly, upregulation of CD44 is often closely associated with abnormal tumor cell behaviors (e.g., proliferation, survival, migration/invasion, and chemoresistance)." (PMID 31293964, 2019). "Tumor cell migration stimulated by LMW-HA is often associated with an epithelial-mesenchymal transition mediated by CD44 through activating PI3K/AKT and TGFβ signaling, while RHAMM is linked to increasing tumor cell migration via regulating ERK and AURKA/beta-catenin pathways." (PMID 31134064, 2019). "Both expressed CSC markers such as CD44, but also expressed genes associated with metastasis, although the authors acknowledge that the mesenchymal-like population may represent tumor associated stroma." (PMID 31366178, 2019). "We compared transcription induced by different physiologic and pathogenic agents in CD44-negative tumor cells, murine embryonic fibroblasts (cd44+/+ and cd44-/- MEFs) and isolated bone marrow derived macrophages from cd44+/+ and cd44-/- mice (in the absence of other cell types)." (PMID 30540779, 2018). "The overexpression of CD44 in tumor cells was strongly associated with therapeutic drug resistance." (PMID 29843359, 2018). "Furthermore, the identification of specific markers associated to different tumor types was used to select side populations enriched in cancer stem cells, such as CD44 and CD133." (PMID 29464039, 2018). "Canonical Wnt signalling promotes the cytoplasmic accumulation and nuclear translocation of β-catenin, which activates T cell factor/lymphoid enhancer factor (TCF/LEF)-mediated transcription of genes that encode tumour invasion and metastasis-promoting molecules (e.g. MMPs and CD44)." (PMID 30285678, 2018). "This suggests that the increase in total CD44 associated with decrease in CD44v and invasion of immune cells may be related to tumor morphological changes." (PMID 29396430, 2018). "CD44 has many splice-variant isoforms, which contribute to heterogeneity in tumor cells." (PMID 30405881, 2018). "Additionally, SR protein levels can affect CD44 alternative splicing implicated in tumor progression." (PMID 29483847, 2018).
tumor (continued). "Tumor microenvironment plays an active role in promoting tumor progression since the growth factor or ligand secreted by CAF may interact with CD44 causing malignant phenotype or triggering tumor promoting downstream signaling." (PMID 29747682, 2018). "Clinically, high frequency of CD44+ cells was associated with tumor grade and poor outcome." (PMID 29861860, 2018). "Furthermore, ATLL-specific EVs from patients with progressive systemic disease prior to treatment were found to carry CD44 and other stemness-associated epitopes, consistent with increasing tumor aggressiveness." (PMID 30400835, 2018). "Overall, certain CD44 variants display different functional roles than CD44s in tumor growth." (PMID 29747682, 2018). "In agreement with this hypothesis, we have demonstrated the causative role of Aurora-A in promoting the expansion of CD44+/CD24-/ER- BTICs responsible for the onset of distant metastases in vMCF-7∆Raf1 tumor xenografts." (PMID 29207686, 2017). "As a consequence of its structural diversity and its ability to interact with a plethora of extracellular ligands, transmembrane proteins as well as cytoplasmic molecules, CD44, and its variants are generally involved in a high number of tumor-promoting processes [reviewed in Ref." (PMID 29062810, 2017). "Thus, elevated CD44 expression in tumor cells in HTM and TM is linked to dissemination / metastases but not necessarily to trastuzumab resistance." (PMID 27835865, 2017). "Interestingly, the expression patterns of c-Met, which is associated with tumor invasion and metastasis were similar to the previously found CD44 expression patterns in HCC." (PMID 29069721, 2017). "Additionally, CD44 expression has been linked to stem cell-like properties as well as tumor progression, cell migration, invasion, metastasis, and poor response to chemo- and radiotherapy." (PMID 29097914, 2017). "Moreover, introduction of 3 × 104 cells of CD44+ fraction caused a tumor formation in 33% of animals, while total population of EC cells used in the same dose, did not cause the formation of ascites." (PMID 28622715, 2017). "Decreased CD44 expression has been associated with a more aggressive PCa phenotype, due to its association with higher grade and pathological stage, correlating with biochemical recurrence and tumour relapse." (PMID 28166834, 2017). "CD44 expression was implicated to be elevated in tumor-initiating cells in many kinds of cancers." (PMID 28279210, 2017). "It is possible that expression of alternative CD44 exons is associated with tumour progression." (PMID 29190904, 2017). "Variant isoforms of CD44 specially, CD44 v6-v10 are overexpressed in both human and animal neoplasms indicating its implication in cancer progression, whereas its removal is associated with inhibition of tumor growth." (PMID 28403901, 2017). "CD44v6, one of the major variants of CD44, could modulate the conjugation of CD44s and hyaluronic acid (HA), or enhance the metastasis of tumor by conjugating with HA." (PMID 28070170, 2017). "The slight decline in CD44/CD24 might be due to the different microenvironment between the tumor and the liver that caused the CSC phenotypic plasticity." (PMID 29062075, 2017). "Finally, we observed changes in the phenotype of tumor-associated adipocytes compared to non tumor associated adipocytes; and evaluated with immunohistochemistry versican, adiponectin, Adipo R1, CD44, and perilipin expression in hATT and hATN slides." (PMID 28173833, 2017). "Ablation of CD44 induced loss of xCT from the cell surface and suppressed tumor growth." (PMID 26785325, 2016). "In addition, binding to the CD44 variants was able to exert significant suppressive effects on apoptosis of tumor cells through the phosphoinositide 3-kinase/Akt pathway." (PMID 27888617, 2016).
tumor (continued). "Overexpression of CD44, Shh, and Gli1 protein was significantly associated with larger tumour size, aggressive gross type, and less differentiated tumour histological type, all of which were clinicopathological features associated with a high metastatic potential." (PMID 26839535, 2016). "In particular, CD44 is closely associated with aggressive behavior and correlates with poor prognosis in a variety of human malignancies, and it has been shown to regulate malignant transformation by inducing tumor cell proliferation, adhesion, and migration." (PMID 27330410, 2016). "Interestingly, some CD44 variants, particularly CD44v8-10 were shown to regulate redox status in cancer cells, and promoted tumor growth." (PMID 27505250, 2016). "Moreover, CD44 downregulation has been associated with increased grade and pathological stage, predicting tumor relapse and biochemical recurrence." (PMID 27323813, 2016). "HA regulates cellular processes through interaction with cell-surface receptors (principally CD44) and has been implicated in numerous biological processes, including embryonic development, wound healing, chronic inflammation, and tumor progression (13, –, 16)." (PMID 25716319, 2015). "CD44 (CD44 molecule) encodes a transmembrane receptor, which is important for lymphocyte activation, recirculation and homing, apoptosis, hematopoiesis, and tumor metastasis." (PMID 25890262, 2015). "The vaccination against CD44 variant (v3–10) was more effective than vaccination with the CD44-standard isoform in eliminating tumor growth in 75% of the vaccinated mice and slowed tumor growth in the remaining animals." (PMID 25954275, 2015). "In this work, we focus on the tumour cells characterised by CD44, CD47 and MET mutations." (PMID 25978366, 2015). "CD44 also exists as a number of splice variants, which are commonly expressed in tumor cells." (PMID 26029216, 2015). "Both CD44s and CD44 variants play complex roles in tumor progression and metastasis." (PMID 26569327, 2015). "Furthermore, we have found that a subset of the PN GSCs undergo differentiation to a MES state in a TNF-α/NF-κB-dependent manner with an associated enrichment of CD44 expressing subpopulations and this can be regulated by the tumor microenvironment." (PMID 26307681, 2015). "Thus, our validated tumor specific delivery of CD44 variant-shRNA has considerable advantage versus other therapeutic strategies." (PMID 26448753, 2015). "Several studies have also found CD117 and CD99 positivity in cases of MCC, and CD44-positive cases may correlate with the high risk of tumor metastasis." (PMID 25663881, 2015). "In addition, several variant isoforms of CD44, known as markers for tumor progression in various malignancies, are transcribed and expressed at the surface upon activation." (PMID 25941526, 2015). "In addition, miR-33b antagomir attenuated the inhibitory effect of cordycepin on the expressions of MMP-2, MMP-9 and CD44 which are associated with tumor invasiveness at mRNA levels." (PMID 25868853, 2015). "Besides, the process of drug resistance induction accompanies activation of anti-oxidation pathway, loss of tumor suppressors function and expression of stem cell marker CD44." (PMID 25635866, 2015). "Expression of CD44 variant proteins has also been implicated in tumor progression." (PMID 26322272, 2015). "In some cases, the role of CD44 in tumor progression could be linked to its function as the main receptor for hyaluronan (HA), a major component of the extracellular matrix (ECM) [reviewed in Ref." (PMID 25904917, 2015). "For example, CD44 is a key mediator of cell-cell and cell-matrix interactions, migration and invasion, and different splicing isoforms of CD44 have been linked with tumor evasion and metastasis in many cancers." (PMID 25749525, 2015). "Thus, together with the oncogenic transformation and the pronounced association of CD44 with oncogenes, HA-CD44 cross-linking initiates signals that promote cell survival in tumor cells." (PMID 25999946, 2015).
tumor (continued). "Recent studies have shown that the percentage of CD44 positive cells expressing variant exons v6 (CD44v6) in tumor cells could be significantly increased by HIF-1α-mediated transcription under hypoxic conditions." (PMID 24647137, 2014). "Overexpression of several CD44 isoforms has been associated with tumor progression, suggesting that these isoforms may have unique signaling properties." (PMID 24122205, 2014). "In vitro, the enzyme showed a dose-dependent cytostatic effect in human and murine tumor cells, and this effect was associated to the proteolytic activity of arazyme, reducing the CD44 expression at the cell surface, and also reducing in vitro adhesion and in vitro/in vivo invasion of these cells." (PMID 24788523, 2014). "These discrepancies may be the result of different methods for detecting CD44 (such as immunohistochemistry (IHC) or PCR) and identifying different CD44 variants in different tumor types." (PMID 24708709, 2014). "Additionally, iCdc42 shifts tumor cell-phenotype from ensheathing/re-arranging vessels, to a loosely associated state, a tendency amplified when CD44 is also reduced." (PMID 25032689, 2014). "CD44v6 is currently the most established tumor antigen among the CD44 splice variants." (PMID 24122205, 2014). "Certain studies have indicated that the overexpression of CD44 in tumors is correlated with increased resistance to radiation therapy and an elevated risk of local recurrence, whereas others have linked poor prognosis to CD44 downregulation on tumor cells, particularly in OSCC." (PMID 24699672, 2014). "However, a much larger panel of cell lines, preferably complemented with expression studies in patient tumor tissue, would be needed in order to draw any conclusions on CD44 variant expression correlated to tumor origin or tumor progression." (PMID 24122205, 2014). "While CD44 has been defined as a cancer stem cell marker in many tumor entities, it remains to be explored whether these cancer stem cells preferentially express CD44s or any CD44 splice variants." (PMID 24122205, 2014). "In addition, we find that enzymatic treatments used to dissociate cells from tissue culture or fresh tumour specimens cause destruction of variant CD44 isoforms at the cell surface whereas expression of the standard CD44 isoform is preserved." (PMID 23437366, 2013). "A switch from CD44 variant isoforms to CD44s can influence the metastatic property of tumor cells." (PMID 23476138, 2013). "CD44 expression has been associated with aggressive behavior of various tumor cells." (PMID 23476138, 2013). "However, treatment with trypsin plus collagenase or collagenase alone consistently caused a decrease in the percentage of cells stained CD44-positive across all tumours and also caused a decrease in the variation in CD44 staining between tumours." (PMID 23437366, 2013). "It was also observed that CD44 isoforms v3, v6, and v10 were significantly associated with advanced primary tumour stage, metastasis, treatment failure, and reduced disease-free survival, indicating that CD44 is a useful marker for HNSCC progression and a possible target for therapy." (PMID 23533441, 2013). "In addition, CD44 plays an important role in tumor cells undergoing an EMT-like process and associated with cancer progression." (PMID 23706092, 2013). "Recent findings indicate that a CD44 variant enhances ROS defense in cancer cells through interaction with and stabilization of xCT, which is the cell surface cystine transporter subunit, thereby promoting tumor growth." (PMID 23803658, 2013). "CD44 has been reported to be associated with aggressive tumor growth and proliferation." (PMID 23308146, 2013). "In addition, several tumor-specific CD44 variants have been described in previous reports; further study is necessary to determine which CD44 variant is expressed in NPC." (PMID 23803658, 2013). "The expression of discrete CD44 splice variants seems to be tumor specific." (PMID 24083250, 2013).
tumor (continued). "The splitting of CD44 was caused by the small fragments of hyaluronan (6.9 kDa and other fragments with molecular weight less than 36 kDa), which in turn led to the increase of tumor cell mobility due to detachment/dissociation of these cells from the tumor." (PMID 22191033, 2012). "Furthermore we managed to gain a glimpse of the role of tumour microenvironment (host) in the modulation of CD44 splice variant expression in conjunction with metastatic potential, as well." (PMID 23151220, 2012). "HA and CD44 have both been implicated in the regulation of tumor growth and metastasis." (PMID 22916191, 2012). "The expression of EpCAM, CD166 and CD44 in CRC is also associated with aggressive tumor phenotypes." (PMID 22267181, 2012). "Kaplan-Meier analysis showed that the presence of CD44+/CD24-/low tumor cells was significantly associated with shorter DFS compared with the absence of CD44+/CD24-/low tumor cells (22.9 ± 2.2 months versus 35.9 ± 3.8 months; Pearson chi-square, 10.696, p = 0.001)." (PMID 22762532, 2012). "Importantly, the interaction between CD44 and HA has been associated with tumor growth and metastasis." (PMID 22916191, 2012). "Such a hypothesis could provide a rational for the association of ALDH with good prognosis or of CD44 with well-differentiated neoplasms." (PMID 22333601, 2012). "Supporting such a hypothesis is data that suggests dominance of CD44s over variant CD44 isoforms with respect to promotion of tumour growth and spread." (PMID 23039365, 2012). "Moreover, the ability to expand CD44+/CD24−/EpCAM+ cells was associated with the ability to support MCF7 tumor growth in vivo (respectively)." (PMID 21957456, 2011). "Since the CD44+/CD24− signature has been associated with tumor initiation, the up-regulation of CD24 population suggest that ATF-126 could decrease the tumor initiating ability of the original line MDA-MB-231." (PMID 21931769, 2011). "After knock down of HAS3 xenografted OSC1 cells still exhibited strong pericellular HA staining concomitant with pronounced CD44 staining suggesting that the elevated CD44 expression may cause binding of stroma derived HA to the tumour cell surface." (PMID 21429221, 2011). "In addition, we found that CD44+CD24-/low tumours were associated with the luminal 1b subtype which, like basal-like tumours, is a subtype defined by basal cytokeratin expression." (PMID 22112299, 2011). "The loss of CD44 in the heterotransplanted tumor sections may be explained by the presence of factors that increase the differentiation of USC-HN1 in situ in contrast to its stem cell-like phenotype that predominates in cell culture or in vivo." (PMID 20175927, 2010). "Given that CD44 is a receptor of hyaluronan, it would be worth investigating whether CD44 expression would also be reduced and associated with tumor progression and a worse patient outcome." (PMID 21124918, 2010). "In the present study, the promoters of the four above-described tumour-associated genes (CD44, Cyclin D2, GLIPR1 and PTEN) were examined for methylation-dependent gene regulation, the participation of MBDs in gene silencing and the histone modifications associated with the respective promoter areas." (PMID 20565761, 2010). "Importantly, Ezrin is also a binding partner for the cytoplasmic part of CD44v6, a splice variant of the proteoglycan-rich cell adhesion molecule CD44 which is implicated in cell activation signalling, invasion and tumour survival." (PMID 19193215, 2009). "CD44 is shown to associate with a proteolytic form of MMP-9 on the surface of various tumor cells." (PMID 19290049, 2009). "Interestingly, SRp55 controls the splicing profile of several tumor-associated genes, among which CD44 and KIT." (PMID 19516963, 2008). "We also asked whether necrosis was associated with alterations of tumor phenotype, and the expression of cell adhesion markers (αvβ3 integrin, CD44/HCAM, osteopontin) was determined." (PMID 19061491, 2008).